MT1A (metallothionein 1A)
Description:
Metallothioneins have a high content of cysteine residues that bind various heavy metals; these proteins are transcriptionally regulated by both heavy metals and glucocorticoids.
Synonyms: MT-1A; MT-IA; MT1S; MT1; MTC
Tractability: PROTAC: ubiquitination databases record sites on it.
Gene: Protein-coding gene on chromosome 16 (56,638,202 to 56,640,087, forward strand). Ensembl gene ENSG00000205362.
Pathways (Reactome):
Cellular responses to stimuli: Metallothioneins bind metals
Gene Ontology:
Molecular function: protein binding; metal ion binding; zinc ion binding
Biological process: cellular response to cadmium ion; cellular response to zinc ion; cellular response to copper ion; detoxification of copper ion; intracellular zinc ion homeostasis; negative regulation of growth
Cellular component: cytoplasm; cytosol; nucleus
Genetic constraint (gnomAD): Loss-of-function variants: 10 observed, 9.74 expected, observed/expected ratio (o/e) 1.03, 90% interval 0.63 to 1.69. That is too few expected variants to judge how well the gene tolerates losing a copy. Missense variants: 69 observed, 76.25 expected, observed/expected ratio (o/e) 0.9, 90% interval 0.74 to 1.11. Synonymous variants: 23 observed, 25.7 expected, observed/expected ratio (o/e) 0.9, 90% interval 0.64 to 1.27.
Homologues: Orthologues: chimpanzee MT1A (98% identical), zebrafish mt2 (62% identical). Paralogues in human: MT1G (90% identical), MT2A (90% identical), MT1H (89% identical), MT1F (87% identical), MT1HL1 (87% identical), MT1B (85% identical), MT1X (85% identical), MT1M (82% identical), MT3 (72% identical), MT4 (62% identical), MT1E (57% identical).